FGFR3 (fibroblast growth factor receptor 3)
Diseases named in the same sentence as FGFR3 in open-access papers (continued):
Sharing a sentence is not in itself a finding about the gene and the disease.
cancer (continued). "This inhibitor differs from earlier TKIs with FGFR‒targeted activity due to its high selectivity for FGFR1, FGFR2, and FGFR3, making this inhibitor particularly attractive for the treatment of FGFR-driven cancers." (PMID 37715207, 2023). "The VM_Score was also found associated with low sensitivity to antiangiogenic and targeted therapies targeting the FGFR3, β-catenin, and PPAR-γ pathways but with high sensitivity to cancer immunotherapy, neoadjuvant chemotherapy, and radiotherapy." (PMID 37197406, 2023). "The distribution of FGFR3 fusion differed from that of FGFR1 and FGFR2 fusions, indicating that the distribution of FGFR fusion genes is cancer type‐dependent." (PMID 37537783, 2023). "Oncogenic FGFR fusions have been identified in several cancers, in which FGFR2 and FGFR3 fusions are mostly observed." (PMID 37493315, 2023). "A recent pan-cancer next-generation sequencing profiling demonstrated that ~7% of cancers harbor gain-of-function FGFR aberrations, with varying frequencies between family members (FGFR1 > FGFR3 > FGFR2 > FGFR4)." (PMID 36839989, 2023). "Other known and possibly yet undiscovered cancer mechanisms are captured by the SKY92, including cell cycle pathways (BIRC5, TOP2A, and CENPE), cell growth and proliferation (FGFR3), DNA repair (FANCF, FANCI, POLQ), and transcription factor (STAT1)." (PMID 34448362, 2022). "MiR-99b was activated when tumor cells underwent EMT reprogramming, and as FGFR3 was a target of miR-99b, it participated in the induction of DTP cancer cells." (PMID 36313710, 2022). "Indeed, we also found in these cancers a significant co-occurrence of FGFR3 SVs with CDKN2A/B and TERT, as has been found previously, suggesting that it may be possible to stratify patients according to these alterations, but clinical data are required to confirm this hypothesis." (PMID 36462464, 2022). "Among newly identified genes, eleven other cancer targets were detected: MPL; ERBB4; VHL; FGFR3; KIT; KDR; PTEN; KRAS; PTPN11; ERBB2; and SMARCB1." (PMID 35621644, 2022). "FGFR is the most common fusion expressed in GBM, specifically fibroblast growth factor receptor 3–transforming acidic coiled coil-containing protein 3 (FGFR3:TACC3), which is the fusion with relevance as a potential target in multiple cancers, including GBM." (PMID 35628161, 2022). "Multivariate analysis also showed that high FGFR3 expression and MIBC subsequent to UTUC were both favorable indicators of cancer-specific death (p = 0.051 and 0.002, respectively)." (PMID 35563543, 2022). "Another study found the expression of SNORD88C was similarly altered mRNA splicing for fibroblast growth factor receptor 3 (FGFR3), which contributes to the progression of multiple cancer types." (PMID 34440039, 2021). "In order to evaluate the clinical value of FGFR3 expression, the correlation between the mRNA expression of FGFR3 and patient overall survival (OS) and recurrence-free survival (RFS) was analyzed across different cancer types." (PMID 34160364, 2021). "FGFR3 downstream signaling pathways include PI3K/AKT and RAS-MEK-ERK, which are common signaling axes that support cancer cell progression." (PMID 33626078, 2021). "Moreover, 5mC cluster 1 (high 5mC score) predicted low sensitivity to cancer immunotherapy, neoadjuvant chemotherapy, and radiotherapy, but high sensitivity to antiangiogenic therapy and targeted therapies, such as blocking the β-catenin, FGFR3, and PPAR-γ pathways." (PMID 34836536, 2021). "Low miR-100 expression has been shown to inversely correlate with FGFR3 expression, longer PFS, and cancer-specific overall survival in BC." (PMID 35223454, 2021).
cancer (continued). "Fusion events were detected in BRAF and FGFR3 in SKCM and HNSC cancer types, respectively, with high expression as compared with wild types." (PMID 34429404, 2021). "In cancers containing genetically altered FGFRs, the most frequent alteration can be found in FGFR1 (49%), followed by FGFR3 (23%), FGFR2 (19%), and lastly FGFR4 (7%)." (PMID 34867402, 2021). "Of 455 440 estimated patients who died of cancer in 2019, 17 019 (3.7%) were estimated to have FGFR2 or FGFR3 alterations." (PMID 31755953, 2019). "Therefore, the discovery and production of FGFR3 inhibitors may be beneficial for cancer patients." (PMID 30999937, 2019). "A recent study showed that FGFR3/TACC3 fusion leads to excessive mitochondrial movement, which provides energy for rapid cell growth, thereby supporting cancer development." (PMID 30999937, 2019). "FGF2 is a molecule significantly more stable than FGF1, and binds to FGFR1, FGFR3 and, to a lesser extent, to FGFR2, allowing it to be a targeting molecule for a large group of FGFR-overexpressing cancers." (PMID 30029518, 2018). "Among the KEGG-annotated pathways regulating stem cell pluripotency and pathways in cancer, several stem cell regulatory transcripts modulated by ADAR111, including AXIN2, MAPK3, and FGFR3, were enriched." (PMID 29203771, 2017). "The genes that were shared by three different cancers (i.e., FGFR3, EPAS1, SRC, and FOXD3) are shown in coral, and the genes that were shared by two types of cancers (i.e., PPARG, FOXO1, CDK4, NKX3-1, PIK3R1, PRKCB and EDNRB) are shown in light pink." (PMID 28178311, 2017). "Among them, several genes were related in cancer pathway such as EGFR, RARA, FGF2, FGFR1, FGFR2, FGFR3, KIT, and CCND1." (PMID 27016420, 2016). "Most of the basal miRNAs targeted factors that have been implicated in the control of luminal biology (FOXA1, ERBB2), adipogenesis (FGFR2, FGFR3) and urothelial differentiation (HOX5/8/13), all of which would be predicted to be suppressed in basal cancers." (PMID 27845906, 2016). "FGFR3 is one of the receptors that promote cell survival by stimulating PI3K/AKT/mTOR signaling, and has been shown to activate AKT and ERK in human cancers." (PMID 26078354, 2015). "We identified two pro-proliferative genes whose protein expression increased upon BCL2 inhibition, FGFR3 (log2ratio = 0.87, p-value = 2.00E-03) and MTOR (log2ratio = 0.53, p-value = 3.49E-02), which have well-known roles in cancer signaling, i.e., FGFR signaling, and mTOR signaling." (PMID 40568132, 2025). "Mutations in pTERT, GPR126, FGFR3, and PIK3CA are cancer-specific and are unlikely to occur in normal cells." (PMID 41515564, 2025). "However, during pathological conditions such as cancer, FGF2 is reported to interact with FGFR3 to promote angiogenesis." (PMID 39766329, 2024). "For the eight identified independent prognostic genes, FGFR3 and SCNN1B were downregulated in cancer cells and could function as protective prognostic indicators for CC." (PMID 38672263, 2024). "This analysis validated the identification of genes that could be specific to cancer biology, such as IL7R, JUN, NR3C1 in Ba/Sq subtype, NPAS2, FOXQ1, GRHL3 in Luminal samples, or CDKN2C, FOXJ1, MEIS2, FGFR3 in both subtypes." (PMID 36944729, 2023).
cancer (continued). "To further investigate the specific inhibitory effect of Pa on FGFR3-dependent cancer cell viability, we evaluated Pa impacts in cancer cell lines for which growth is independent of FGFR3 activity." (PMID 37824212, 2023). "Remarkably, regardless of cancer types, FGFR3 fusions were almost exclusively in the form of FGFR3-TACC3 (94%, 47/50), generated by translocations in chromosome 4." (PMID 36369474, 2022). "FGFR3 is an RTK of the FGFR family that is responsible for cell growth, differentiation, and migration in a wide variety of cell types and is present in MM and a variety of cancers." (PMID 36145532, 2022). "Mutations in the telomerase reverse transcriptase (TERT) promoter and the fibroblast growth factor receptor 3 (FGFR3) gene are sometimes seen in LS and have been proposed as novel biomarkers of urothelial cancer (UC), which is the third most common cancer type in certain subsets of LS families." (PMID 35457101, 2022). "Interestingly, the mRNA levels of FGFR1 and FGFR3 in EPN tissues across all EPN subtypes were at least as high as the levels in the well-described FGFR-driven cancer cell models NCI-H1703 (FGFR1, NSCLC) and Hep3B (FGFR3, HCC) (respectively)." (PMID 34046693, 2021). "Although emerging evidence supports the role of FGFR3 in individual cancer types, no pan-cancer analysis is available." (PMID 34160364, 2021). "First of all, this study was a pan-cancer analysis of FGFR3 genetic alterations and lacked an in-depth investigation and analysis of individual cancer types." (PMID 34160364, 2021). "Contrary to this, genetic alterations in fibroblasts growth factor receptor 3 (FGFR3), a potent receptor-tyrosine kinases (RTK) involved in growth and proliferation of cancer cells, were significantly higher in HPV-positive vs. HPV-negative tumours (13.95% vs 1.73%, p=0.017)." (PMID 34631566, 2021). "The Cancer Genome Atlas (TGCA) project recently indicated that the MAPK/ERK and PI3K/AKT pathways were potential BCa driver genes and that these downstream cascades were mainly activated by FGF receptors (FGFRs), especially FGFR1 and FGFR3 in BCa." (PMID 33918555, 2021). "Moreover, reduced oxygen levels significantly increased inhibition of FGFR3-downstream signaling and improved the anticancer activity of both cobalt(iii) complexes against ABL- and FGFR-dependent human cancer cell models." (PMID 34046181, 2021). "Despite some clinical success with selective FGFR inhibitors in cancers with FGFR3 molecular alterations, these therapies are not curative and there remains a substantial patient population that harbour intrinsic resistance to these drugs." (PMID 32370101, 2020). "Thus, features such as EPB41, PSMA1, FGFR3, MRAS, and LEP which were involved in cancer-related pathways and with high PPI degrees (>/ = 10) were considered as PRBs for further analysis." (PMID 32528533, 2020). "Therefore, cancer‐related RTK become preferable targets for ADC development, e.g. RON, PTK7, FLT3, FGFR2, FGFR3, ERBB3, KIT and EPHA2." (PMID 31116512, 2019). "Moreover, several mRNAs in the ceRNA network were enriched in pathways involved in cancer such as WNT11, FGFR3, PLCB4, and IKBKB." (PMID 31729423, 2019). "Estimated number of patients with advanced cancer expressing an FGFR2 or FGFR3 alteration eligible for off-label use of erdafitinib by cancer type; number of studies investigating FGFR-targeting drugs for patients with cancer; and number of ongoing clinical trials on erdafitinib by cancer type." (PMID 31755953, 2019). "It would be interesting to determine whether this FGFR3/MYC feedback loop, mediated by AKT and p38, also operates in other types of human cancers expressing FGFR3‐TACC3." (PMID 29463565, 2018). "The finding that HDAC6 deficiency or inhibition suppressed the accumulation of both wild type FGFR3 and mutant activated FGFR3 led to studies performed here that tested the effectiveness of tubacin and HDAC6 inhibition as a therapeutic strategy in FGFR3-dependent cancers." (PMID 29423038, 2018).
cancer (continued). "We recently found that efficient accumulation of a constitutively active FGFR3 mutant which is responsible for the lethal human disorder thanatophoric dysplasia type II (TDII) and is found in some bladder and other cancer types, was dependent on HDAC6 in cultured cells and in vivo." (PMID 29423038, 2018). "We note that therapies that inhibit FGFR3 signalling in FT3-positive cancers would not tackle the reduction of TACC3 levels at the mitotic spindle, and mitotic defects will still be present in these cells." (PMID 28855393, 2017). "This function of FT3 is specific to TACC3 as inhibition of FGFR3 signalling does not rescue the TACC3 level on the spindle in these cancer cells." (PMID 28855393, 2017). "IL-27 caused, in both cell lines, a significant down-regulation of a series of anti-angiogenesis related genes namely FGFR3, PTGS1 and, particularly, FLT1, which has been reported to be firmly and strongly expressed in hPCa and involved in cancer cell proliferation via autocrine VEGF signaling." (PMID 24681516, 2014). "Based upon the potential importance of NFκB activity and gene expression profiling results that implicate NFκB signaling as a target for the FGFR3 and TAK1 interaction, we evaluated the combined contribution of FGFR3 and TAK1 to NFκB activity in cancer cells using an NFκB-luciferase reporter assay." (PMID 24466111, 2014). "Some of the two latter cancer tissues displayed areas with strong staining, but it was always highly heterogeneous, some regions totally lacking FGFR3, on the same sections." (PMID 23902722, 2013). "FGFR3 and many other growth factor receptors participate in the activation of the RAS-kinase signaling pathway, thus leading to increased cell proliferation, motility, and cancer transformation through hyperplasia of normal urothelium." (PMID 24298280, 2013). "In cancer tissues, we found a significant decrease of FGFR3 RNAs in PDAC as compared to normal pancreas, regardless of the splice variant, which balance did not change." (PMID 23902722, 2013). "Aberrant activation of FGFR3 and STAT3 has been observed in a multitude of human cancers." (PMID 24115909, 2013). "However, in contrast to other cancer types, we found that the expression of FGFR3 is not necessarily stronger in higher grades of cancer." (PMID 41228379, 2025). "Second, almost all studies of umiRNA and ucfDNA did not indicate whether their analyses are specific only for BCa, and some of the candidate genes that have diagnostic value in BCa, such as FGFR3 and DMRTA2, are generally not rare in other cancers." (PMID 36012417, 2022). "In addition, bile could be used to detect genomic alterations in BTC that are cancer-targeted therapy-related candidates, such as the ERBB2, FGFR1, FGFR2, FGFR3, KRAS, and WNT pathways." (PMID 36091112, 2022). "The cancer target PDB ID 1RY0 (AKR1C3) showed the highest interactions with the majority of the NCs, followed by 1HFQ (DHFR), 3ZGC (NFE2L2), 4AF3 (AURKB), 4K33 (FGFR3), 5P21 (HRAS), 2I0V (CSF1R), and 3ZIM (PIK3CA) protein targets and least interaction was found with the 1M9Z (TGFBR2) protein." (PMID 36387366, 2022). "HPV-score was considered negatively correlated with genes from the FGFR3 pathway and cell cycle regulation and positively correlated with epithelial-mesenchymal transition (EMT) biological functions, which might promote cancer cell proliferation, invasion, and migration." (PMID 34925445, 2021). "Notably, TIE1, KIT, NTRK1, FGFR3, CSF1R, and INSRR were shared by both cancers." (PMID 34944663, 2021). "Therefore, the inhibition of FGF2, FGFR3, and FGFBP1 may enhance the efficacy of chemotherapy, which is hopeful to make it an irreplaceable sensitizing target for cancer treatment." (PMID 33381388, 2020).
cancer (continued). "In addition, it is reported that four downregulated genes of AKT1, CLECSF7, FGFR3, and LRP6 served as candidate genes and correlated with suppressing the biological processes in the cell cycle of cancer progression and the downstream signaling pathways of malignancy of melanocytic tumorigenesis." (PMID 33250779, 2020). "Furthermore, by screening through the criteria of the PPI network, cancer-related pathway and TRS modeling, essential features with gene symbols of EPB41, PSMA1, FGFR3, MRAS, LEP, C7orf46, LOC285000, LBP, ZNF35, SLC30A3, LECT2, RNF7, and DYNC1I1 were identified as PRBs for COAD patients." (PMID 32528533, 2020). "Therefore, it is no surprise to aim FGFR3 as potential therapeutic target for understanding the disease development and cancer therapy." (PMID 31535232, 2019). "The CCND1 gene is amplified in a variety of cancers, including approximately 20% of muscle-invasive and non-muscle-invasive bladder cancers, and its upregulation by mutant FGFR3 is therefore predicted to contribute to FGFR3-dependent oncogenesis." (PMID 29423038, 2018). "The cancers in which FGFR gene amplifications are most frequent include bladder urothelial carcinomas (FGFR1), squamous cell lung cancer (FGFR1), head and neck squamous cell cancer (FGFR1), uterine carcinosarcoma (FGFR3), breast adenocarcinoma (FGFR1), and gastric adenocarcinoma (FGFR2)." (PMID 26224133, 2015). "FGFR2 and FGFR3 were also up-regulated in some of the cancer cells, but not as markedly as FGFR1." (PMID 26201468, 2015). "Ligand responsiveness in MGHU3 cells may result from the stimulation of other FGF receptors, which we have not examined in detail, as FGFR3 is the most relevant FGF receptor for this cancer type." (PMID 24466111, 2014). "Thus, we suspect that the preclinical data underestimate the potential impact of FGFR3-based therapy in patients with low-grade, non-muscle invasive FGFR3-mutant cancers." (PMID 23468956, 2013). "Meanwhile, HPV-positive and -negative tonsil cancers may likely have different preferences for cancer-related pathways and detailed somatic mutations: HPV-positive tumors tend to have higher rates of RB1, HRAS, and FGFR3 mutations." (PMID 36979829, 2023). "The OD-BRE-0438 model with the most resistant phenotype, as evidenced by the shortest median PFS, showed statistically significant upregulated gene expression of FGF1, FGF7, and FGF8 ligands in cancer cells, while FGFR1, FGFR2, or FGFR3 were not upregulated." (PMID 40227585, 2025). "No statistical difference was observed in the abundance of VGFR2, PGFRA, FGFR3, ERBB2, NTRK2 and TIE2 among the healthy, non-tumorous (histologically normal) and tumorous livers from cancer patients." (PMID 36890818, 2023). "In non-tumorous (histologically normal) tissues from cancer patients, there were correlations between TIE2 and FGFR1, EPHA2 and VGFR3, FGFR3 and PGFRA (p < 0.05)." (PMID 36890818, 2023). "In addition to FGFR1 and FGFR3, studies have shown that insulin-like growth factor 1 (IGF-1) and the lipid hydroperoxidase, GPX4, could activate the PI3K/AKT and ERK pathways to induce the EMT program, and IGF-1R phosphorylation in cancer cells led to the production of DTPs." (PMID 36313710, 2022). "Among these 16 negative-specific TMM genes, only FGFR3 and TAL1 were cataloged by the curated Cancer Gene Census." (PMID 35953846, 2022). "Indeed, according to this model, it appears that FGFR3 is founded in a negative cross-talk from FGFR3 to EGFR, thus indirectly inhibiting the growth factor receptor EGFR, which is also a documented target in cancer therapies." (PMID 29515890, 2018).